GSN (gelsolin)
Diseases named in the same sentence as GSN in open-access papers (continued):
Sharing a sentence is not in itself a finding about the gene and the disease.
Sepsis (32 papers, 2008 to 2026). Sepsis is defined as life-threatening organ dysfunction caused by a dysregulated host response to infection. "This narrative review summarizes recent evidence on the potential of circulating microRNAs (miRNAs) such as miR-150, miR-146a, miR-223, miR-155, miR-122, and miR-4772-5p and plasma gelsolin (pGSN) as diagnostic and prognostic markers in sepsis." (PMID 41301539, 2025). "Biomarkers associated with endothelial integrity and sepsis severity are increased in COVID-19, while plasma gelsolin and IL-1α levels are decreased in patients who die from COVID-19." (PMID 33232303, 2021). "Excess actin in the plasma reduces the level of scavenger actin-binding proteins (GSN, Gc-globulin, thymosin beta-4), and excess actin can also be found in the urine of the patients who could have a diagnostic value regarding sepsis-related AKI." (PMID 37836706, 2023). "Also, decreased gelsolin plasma concentration was associated with increasing burn sizes and the severity of sepsis in human patients." (PMID 37888177, 2023). "In burn patients, plasma gelsolin levels decreased with increasing burn sizes, and increasing incidence of septic complication, and correlated with development of multiple organ dysfunction syndrome and enhanced burn- and sepsis-associated mortality." (PMID 30149613, 2018). "As plasma gelsolin has the ability to bind actin, blood gelsolin depletion was observed in diverse states of inflammation associated with tissue injury and actin release: adult respiratory distress syndrome, sepsis, myocardial infarction, hepatitis, myonecrosis and rheumatoid arthritis." (PMID 21040581, 2010). "• Admission plasma gelsolin levels were associated with the occurrence of severe sepsis." (PMID 18706105, 2008). "Gradual recovery of gelsolin concentration is most likely associated with effective treatment, which would be in line with a study demonstrating greater than two-fold increases of gelsolin blood levels resulting from continuous sedation therapy in patients with severe burn-induced sepsis." (PMID 30149613, 2018). "Moreover, cytoplasmic gelsolin depletion is observed in diverse states of inflammation that are associated with tissue injury and actin release, including hemorrhagic shock, early sepsis, trauma, and rheumatoid arthritis." (PMID 21936896, 2011). "The number of patients with severe sepsis enrolled in the time course study is inadequate to allow definitive conclusions to be drawn, and the study does not unequivocally elucidate the role played by plasma gelsolin in sepsis or the association of plasma gelsolin with cytokines." (PMID 18706105, 2008). "Gelsolin levels were compared among these groups and changes in these levels were observed over time to determine whether these changes were associated with outcomes in patients with severe sepsis." (PMID 18706105, 2008). "Human studies investigating circulating microRNAs (miRNAs) and plasma gelsolin (pGSN) in sepsis and severe infection." (PMID 41301539, 2025). "Experimental and preclinical studies on circulating microRNAs (miRNAs) and plasma gelsolin (pGSN) in sepsis." (PMID 41301539, 2025). "Although plasma gelsolin (pGSN) and circulating microRNAs (miRNAs) are different biomarker types, both indicate the severity and regulation of the host response in sepsis." (PMID 41301539, 2025). "Major proteins of the actin scavenger system (GSN, Gc) exhibited decreased serum levels in patients with severe inflammation compared with controls and a further fall was observed in sepsis." (PMID 41462865, 2025). "Among emerging molecular biomarkers, microRNAs (miRNAs) and plasma gelsolin (pGSN) have garnered increasing attention for their complementary roles in immune regulation and tissue injury during sepsis." (PMID 41301539, 2025).
Sepsis (continued). "Blood gelsolin levels are decreased markedly in various medical conditions such as acute respiratory distress syndrome, myocardial infarction, sepsis, major trauma, malaria, liver injury, and inflammatory joint diseases." (PMID 36902587, 2023). "During acute injury and inflammation levels of plasma, GSN protein levels were decreased, and recombinant plasma GSN administration to animals improves outcomes following burn or sepsis injuries." (PMID 31781269, 2019). "The potential usefulness of pGSN as a sepsis biomarker is encouraged by reports indicating depletion of plasma gelsolin both in an animal model of sepsis and in critically ill surgical patients, particularly those diagnosed with severe sepsis." (PMID 30149613, 2018). "It has already been reported that recombinant human pGSN (rhp-GSN) can remit some inflammatory diseases in the animal model, such as burn injury, middle cerebral artery occlusion, and sepsis." (PMID 28377587, 2017). "Plasma gelsolin levels are significantly decreased in major trauma, burns, surgery and sepsis, whereas recovery of circulating gelsolin has been correlated with improvement in patient outcomes." (PMID 29142235, 2017). "It has been reported that the injection of the recombinant gelsolin into animal models in appropriate doses can decrease mortality and reduce the damage due to hyperoxia, burn, and sepsis conditions." (PMID 28377587, 2017). "We demonstrated that, although almost all the patients had decreased gelsolin levels after extensive burn injuries, the lowest levels were associated with less SOFA score and more complicated disease courses (e.g. sepsis or septic shock)." (PMID 22069445, 2011). "We studied plasma gelsolin levels at the time of admission to the intensive care unit (ICU) in patients with severe sepsis." (PMID 18706105, 2008). "Ninety-one patients who were diagnosed with severe sepsis at admission to a surgical intensive care unit were enrolled, and admission plasma gelsolin levels were recorded." (PMID 18706105, 2008). "The plasma gelsolin level at the time of admission in the severe sepsis group was 20.6 ± 11.7 mg/l, which was significantly lower than that of 15 nonseptic critically ill patients (52.3 ± 20.3 mg/l, P < 0.001)." (PMID 18706105, 2008). "Admission plasma gelsolin levels correlated with severity of sepsis, whereas recovery of plasma gelsolin levels correlated with clinical improvement." (PMID 18706105, 2008). "In the study conducted by Lee and coworkers, depletion of plasma gelsolin in animal models of sepsis occurred 6 hours after a septic challenge with either endotoxin (lipopolysaccharide) or a polymicrobial challenge after caecal-ligation and puncture." (PMID 18706105, 2008). "Logistic regression revealed that among the seven candidate risk factors (admission plasma gelsolin, IL-6, IL-10, TNF-α, albumin, age and sex), admission plasma gelsolin was the only independent factor able to predict the occurrence of severe sepsis." (PMID 18706105, 2008). "This study suggests that plasma gelsolin levels are a valuable marker of severe sepsis in surgical ICUs." (PMID 18706105, 2008). "Levels of plasma gelsolin decrease during acute injury and inflammation, and administration of recombinant plasma gelsolin to animals improves outcomes following sepsis or burn injuries." (PMID 18822171, 2008). "Little is known about the course of plasma gelsolin levels over time in patients with severe sepsis." (PMID 18706105, 2008). "In animal models of sepsis, depletion of plasma gelsolin correlates with elevated circulating levels of actin and gelsolin replacement modifies the cytokine profile and improves survival." (PMID 18706105, 2008). "Additionally, gelsolin replacement therapy has proven effective in some animal models, such as those involving sepsis." (PMID 40106086, 2025). "Besides microRNAs, plasma gelsolin (pGSN) has emerged as a significant circulating biomarker of the host’s inflammatory and immune response in sepsis." (PMID 41301539, 2025).
Sepsis (continued). "Similarly, plasma gelsolin (pGSN) is an actin-binding protein with extracellular anti-inflammatory and cytoprotective properties; its levels decrease significantly during sepsis and correlate with disease severity and adverse outcomes." (PMID 41301539, 2025). "From a clinical perspective, circulating microRNAs (miRNAs) and plasma gelsolin (pGSN) may support precision strategies for managing sepsis." (PMID 41301539, 2025). "Since GSN has a protective role by being an actin scavenger protein, numerous studies reported decreasing serum GSN concentrations in various clinical conditions (e.g., trauma, acute liver failure, myocardial infarction, sepsis)." (PMID 37215727, 2023). "Simultaneously, it was confirmed the plasma gelsolin level recovery was correlated with clinical improvements in survivors of severe sepsis, which clearly indicates that daily assessments of pGSN concentrations are required for accurate sepsis case prediction." (PMID 30149613, 2018). "Thus, our proteomic results showing increased levels of actin and decreased levels of gelsolin in plasma are consistent with previous reports and stress important changes in the cytoskeleton during sepsis." (PMID 29142235, 2017). "Gelsolin levels have been reported to decline in many diseases of humans as well as in animals and there are several reports in the literature regarding use of gelsolin for treatment of sepsis, burn, brain inflammation, diabetes." (PMID 26426535, 2015). "Accordingly, gelsolin replacement might be considered as a potential therapy for the lethal condition of sepsis." (PMID 21936896, 2011). "Combined with previous reports, this study suggests that early determination of plasma gelsolin level could facilitate early diagnosis of severe sepsis." (PMID 18706105, 2008). "The aim of the study was to investigate plasma gelsolin levels in severe septic patients and to determine whether these levels predict the severity or clinical outcome of severe sepsis." (PMID 18706105, 2008). "GSN can act as an actin scavenger by binding free actin subunits, which may be released into the extracellular space and plasma after cell damage in disease states such as sepsis and acute respiratory distress syndrome." (PMID 39352744, 2024). "In addition to the well-documented effect of plasma gelsolin in trauma injuries, sepsis, infections, and neurological disorders, single studies present the potential of pGSN in other diseases, including diabetes, pre-eclampsia, congenital genetic syndromes, or rhabdomyolysis." (PMID 30149613, 2018). "Repletion with exogenous gelsolin improved survival rate of both endotoxemic and CLP-treated mice and rats, and altered inflammatory cytokine expression 24 h after insult, which emphasizes the validity of reversing pGSN deficiency as an effective treatment option for sepsis." (PMID 30149613, 2018). "These are based on promising results from animal experiments, where markedly improved outcomes have been noted (for example, in sepsis, burn brain inflammation and diabetes in mice and rats) after exogenous administration of gelsolin, thereby advocating a need for the “gelsolin replacement therapy”." (PMID 26426535, 2015). "In addition, its deficiency has been found to correlate with septic mortality and prognosis, suggesting that gelsolin might play a crucial protective role in the course of sepsis." (PMID 21936896, 2011). "Admission plasma gelsolin level was a independent risk factor that correlated with occurrence of severe sepsis, although it did not significantly differ between surviving and nonsurviving patients with severe sepsis." (PMID 18706105, 2008). "• Plasma gelsolin may be a valuable marker for severe sepsis." (PMID 18706105, 2008). "Studies suggest that plasma gelsolin may play a crucial role in the pathophysiology of sepsis." (PMID 18706105, 2008).
Sepsis (continued). "Consequently, gelsolin levels significantly may decrease after tissue injury in various conditions, including acute respiratory distress syndrome, acute injury to the lungs and liver, sepsis, major trauma, prolonged hyperoxia, and malaria." (PMID 38034020, 2023). "We aimed to facilitate the diagnosis and prognosis of sepsis-related organ dysfunction through analyzing presepsin (PSEP) and gelsolin (GSN) levels along with a novel marker, the presepsin:gelsolin (PSEP:GSN) ratio." (PMID 37215727, 2023). "In addition, gelsolin levels have been stated to decline in a plethora of diseases, and supplementing exogenous recombinant human gelsolin (rhuGSN) alleviated distress symptoms in many disease conditions including sepsis, inflammation, diabetes, thrombosis, and pulmonary thromboembolism." (PMID 32104532, 2020). "Myeloid cell-specific GSN-knockout mice exhibited aggravated inflammatory responses in models of MSU-induced peritonitis, folic acid-induced acute tubular necrosis, and LPS-induced sepsis." (PMID 39179640, 2024). "Based on these reports, it was proposed that apart from serum GSN concentrations measurements, simultaneous assessment of serum actin and determination of actin/gelsolin ratio (A/GSN ratio) might be useful in the evaluation of SIRS and sepsis severity." (PMID 30149613, 2018). "The admission gelsolin levels were significantly decreased in severe sepsis (20.6 ± 11.7 mg/l) compared with nonseptic critically ill patients (52.3 ± 20.3 mg/l; P < 0.001) and healthy control individuals (126.8 ± 32.0 mg/l; P < 0.001)." (PMID 18706105, 2008). "Recovery of plasma gelsolin levels was observed late in the course in survivors but not in nonsurvivors with severe sepsis." (PMID 18706105, 2008). "• Admission plasma gelsolin levels in patients with severe sepsis were lower than those in nonseptic, critically ill ICU patients or healthy control individuals." (PMID 18706105, 2008). "Twenty-three patients with severe sepsis and 15 nonseptic critically ill patients had daily plasma gelsolin levels measured consecutively after their ICU admission." (PMID 18706105, 2008). "• Survivors of severe sepsis exhibited substantial recovery of their depressed plasma gelsolin levels, whereas the gelsolin levels in nonsurvivors remained at or below their depleted admission levels." (PMID 18706105, 2008). "The present study revealed that plasma gelsolin levels measured at the time of ICU admission in patients with severe sepsis were lower than those in nonseptic critically ill patients and healthy control individuals." (PMID 18706105, 2008). "Survivors of severe sepsis exhibited substantial recovery of their depressed plasma gelsolin levels, whereas gelsolin levels in nonsurvivors remained at or below their depleted admission levels." (PMID 18706105, 2008). "Among survivors depressed plasma gelsolin levels appeared to recover after day 11, whereas plasma gelsolin levels remained low or even decreased further in the nonsurvivors with severe sepsis." (PMID 18706105, 2008). "In the present study we found that admission plasma gelsolin levels were lower in patients with severe sepsis than in nonseptic critically ill ICU patients and healthy control individuals." (PMID 18706105, 2008). "The admission levels of plasma gelsolin in both severe sepsis and nonseptic critically ill patients were significantly different from those of the 15 healthy control individuals (126.8 ± 32.0 mg/l; P < 0.001)." (PMID 18706105, 2008). "However, previous research has established that the presence of particulate actin in the bloodstream is indicative of sepsis-induced cell damage, and low levels of plasma GSN have been identified as a marker for a negative prognosis in sepsis." (PMID 38343439, 2023).
Sepsis (continued). "Interestingly, a reduced plasma gelsolin level was also recognized as a potential biomarker in precancerous conditions such as inflammation, sepsis, and HIV through releasing of inflammatory mediators, which suggests the clinical usefulness of recombinant gelsolin." (PMID 34947825, 2021). "Further studies confirmed that admission plasma gelsolin levels are also lower in neonatal infants and adult patients with severe sepsis than in non-septic critically ill patients in the ICU, including those diagnosed with systemic inflammatory response syndrome (SIRS)." (PMID 30149613, 2018). "Although cerebral complications have been related to increased mortality in severe sepsis and major burn victims, attenuation of neuroinflammation might not account for all of the benefit of gelsolin in reducing burn-induced mortality in our study." (PMID 21936896, 2011). "Additionally, we measured daily plasma gelsolin levels in critically ill patients admitted to a surgical ICU with severe sepsis and without sepsis." (PMID 18706105, 2008). "Furthermore, this study demonstrated that the depletion of plasma gelsolin recovered with clinical improvements in survivors of severe sepsis, whereas the gelsolin level in nonsurvivors remained low." (PMID 18706105, 2008). "We have previously reported that serum gelsolin (GSN; MW = 83 kDa) as a major member of the actin scavenger system showed superior performance in differentiation of sepsis from the non-septic severe inflammatory state, and it might be a potential predictor of 14-day mortality in sepsis." (PMID 41462865, 2025).